IL1B (interleukin 1 beta)
Diseases named in the same sentence as IL1B in open-access papers (continued):
Sharing a sentence is not in itself a finding about the gene and the disease.
overnutrition (4 papers, 2020 to 2024). An imbalanced nutritional status resulting from excessive intake of nutrients. "In the myocardium, early overnutrition was associated with a significant increase in the gene expression of the proinflammatory markers IL-1β (p < 0.05), IL-6 (p < 0.01), TNF- α (p < 0.05), and LO (p < 0.05), and the pro-oxidant enzymes NOX-1 (p < 0.05) and NOX-4 (p < 0.01)." (PMID 32093229, 2020). "Overnutrition and its consequences, such as oxidative stress, potentiate the production of inflammatory cytokines, particularly IL-1β, TNF-α, IL-6, and many other cytokines and chemokines that are IL-1β-dependent." (PMID 36160451, 2022). "After 3 consecutive days of overnutrition, zMIR fish exhibit more severe ER stress in β cells, triggering Ripk3-mediated induction of il1b expression and subsequent macrophage recruitment, β cell loss, and glucose dyshomeostasis." (PMID 36001973, 2022).
panic disorder (4 papers, 2018 to 2022). An anxiety disorder characterized by multiple unexpected panic attacks with persistent concern of recurring attacks. "Those with panic disorder have also demonstrated increased IL-1β and IL-6." (PMID 33208194, 2020). "Higher levels of IL-1β and IL-6 in panic disorder patients may interfere with differentiation and activation of naïve CD8+ T, possibly reducing inflammation." (PMID 33208194, 2020). "In particular, patients with panic disorder (PD) present an inflammatory response due to elevated levels of pro‐inflammatory cytokines, such as interferon gamma (IFN‐γ), tumor necrosis factor alpha (TNF‐α), interleukin (IL) 6, and IL‐1β." (PMID 35588458, 2022).
papillary thyroid carcinoma (4 papers, 2017 to 2021). "Herein, we reported the nuclear RORγt, IL-17A, IL-23 and IL-1β in tumor cells of papillary thyroid cancer." (PMID 32139737, 2020). "A case-control study of 93 patients with papillary thyroid carcinoma (PTC) and 324 controls found that IL-1β rs1143627 may be associated with risk of PTC in a Korean population." (PMID 28676856, 2017).
penile cancer (4 papers, 2015 to 2023). A primary or metastatic malignant neoplasm that affects the penis. "Besides, IL-1A and IL-1B, which have been identified as the key machineries in inflammation modulation to cause penile cancer, were also successfully enriched in the current GO terms." (PMID 26158897, 2015). "Since there is no direct relationship between observed polymorphism and IL-1RN level, our results are the first that show the possible lack of IL-1RN blockage of the local inflammatory function of Il-1A and IL-1B in penile cancer." (PMID 37763742, 2023). "The highest levels were noted for IL-1B and IL-1A (ca. 385 and 165 times, respectively) in penile cancer vs. control group." (PMID 37763742, 2023). "IPA identified potential upstream regulators that explain the transcriptional changes of human penile cancer, which included activated targets by pro-inflammatory factors such as TNF, CSF2, IFNγ, IL1B, and inhibited targets by TGFβ1." (PMID 32358507, 2020).
pheochromocytoma (4 papers, 2022 to 2025). "MALAT1 was also proven to upregulate pro-inflammatory factors in poststroke mice, and MALAT1 knockdown partially reduced the levels of TNF-α, IL-6, and IL-1β in mouse pheochromocytoma cell lines after oxygen and glucose deprivation/reperfusion." (PMID 40869277, 2025).
plaque psoriasis (4 papers, 2020 to 2025). "Although both IL‐1β and IL‐36 are implicated in the pathogenesis of plaque psoriasis, their quantities are higher in GPP, where the IL‐36 signalling pathway plays a pivotal role." (PMID 40181552, 2025). "Pre-selected SNP sets were associated with psoriasis vulgaris analysis, which was used to identify four SNP-associated targeted therapy efficiencies: IL1β (rs1143633), IL4 (IL13) (rs20541), IL23R (rs2201841), and TNFα (rs1800629) genes." (PMID 33383665, 2020).
POEMS syndrome (4 papers, 2015 to 2025). POEMS syndrome is a paraneoplastic syndrome characterized by polyradiculoneuropathy (P), organomegaly (O), endocrinopathy (E), clonal plasma cell disorder (M), and skin changes (S). "Second, in POEMS syndrome there is overproduction of proinflammatory cytokines, including TNFα, IL1β, IL10, IL6, VEGF, similarly to what is observed in MCD and KICS, suggesting that these three clinical entities partially overlap." (PMID 25607954, 2015). "POEMS syndrome, on the other hand, is characterized by significantly elevated VEGF levels, along with increased inflammatory cytokines such as IL‐1β, IL‐6, and TNF-α." (PMID 41293360, 2025). "The pathogenesis of POEMS syndrome is not well understood but it is thought to involve overproduction of proinflammatory cytokines, such as vascular endothelial growth factor (VEGF), interleukin-1 beta (IL-1B), interleukin-6 (IL-6), and tumor necrosis factor-alpha (TNF-alpha)." (PMID 34692278, 2021).
primary progressive MS (4 papers, 2013 to 2025). "In controls, there were positive correlations between circulating leptin and resistin with TNF-α and IL-1β in subgroup analysis, the highest levels of TNF-α, IL-1β, hs-CRP, resistin and leptin were observed in primary progressive-MS (PP-MS) patients." (PMID 24098530, 2013). "Likewise, PBMCs from patients with primary progressive MS (PPMS) overexpress pro-inflammatory cytokines, including IL-1β, IL-6, TNF, and NLRP3, with monocytes being the primary driver of this profile." (PMID 40710307, 2025).
pulmonary sarcoidosis (4 papers, 2015 to 2025). Sarcoidosis affecting the lung parenchyma. "An imbalance between the levels of IL-1β and IL-1 receptor antagonist has been observed in the BALF of patients with pulmonary sarcoidosis." (PMID 33330556, 2020). "The serum levels of IL-6 and IL-1β were not significantly different between patients with pulmonary sarcoidosis or EPS or between healthy controls (data not shown)." (PMID 25866481, 2015).
radiation pneumonitis (4 papers, 2008 to 2024). Inflammation of the lung due to harmful effects of ionizing or non-ionizing radiation. "IL-1β and IL-6 are the major cytokines in radiation pneumonitis." (PMID 39575431, 2024). "The aim of the present study was to investigate the prognostic value of TNF-α, IL-1β, IL-6 and TGF-β1 plasma levels to predict radiation pneumonitis and to evaluate the impact of tumour-derived cytokine production on circulating plasma levels in patients irradiated for NSCLC." (PMID 18682839, 2008). "In a rat model of radiation pneumonitis (RP), radiotherapy increased the mRNA expression level of AIM2, which further triggered the release of IL-1β and induced RP, suggesting that the activation of the AIM2 inflammasome by radiotherapy may contribute to the pathogenesis of RP." (PMID 35004305, 2021). "Radiation pneumonitis develops within hours or days of lung IR and is accompanied by increased capillary permeability, leukocyte infiltration, and release of cytokines, such as transforming growth factor β (TGF-β), interleukin 6 (IL-6), tumor necrosis factor alpha, and interleukin-1 beta (IL-1β)." (PMID 32811815, 2020).
rhabdomyolysis (4 papers, 2020 to 2025). Necrosis or disintegration of skeletal muscle often followed by myoglobinuria. "RJ administration at 100 and 200 mg/kg doses during rhabdomyolysis significantly decreased renal production of IL-1β compared to the Rhabdo group (P<0.001)." (PMID 40666175, 2025). "NLRP3 depletion decreased the mRNA expression of inflammatory cytokines, including TNF-α, IL-1β, and IL-6, induced by rhabdomyolysis." (PMID 33202867, 2020). "Since ibrutinib failed to prevent kidney injury and exacerbated the fibrotic phenotype in the UUO model, we verified the ability of ibrutinib to modify outcomes in mice submitted to rhabdomyolysis, a cause of AKI at risk of subsequent CKD also displaying increased expression of Il1b and Nlrp311." (PMID 34099830, 2021). "β-defensin 3, thus, together with NGAL, TNFα, IL-1β and IL-6 are the proinflammatory mediators directly responsible for the worst outcome of CRAMP-/- mice subjected to the rhabdomyolysis model." (PMID 33456345, 2021). "TNFα, IL-1β and IL-6 levels were significantly increased in kidney tissue from CRAMP-/- mice subjected to the rhabdomyolysis model compared with the wild-type counterparts (p < 0.01, p = 0.02 and p = 0.03, respectively)." (PMID 33456345, 2021).
SAPHO syndrome (4 papers, 2022 to 2024). SAPHO syndrome (acronym for Synovitis, Acne, Pustulosis, Hyperostosis and Osteitis) is an auto-inflammatory disease, mainly characterized by the association of neutrophilic cutaneous involvement and chronic osteomyelitis. "Interleukin-1 beta (IL-1β), a key pro-inflammatory cytokine, plays a significant role in the pathogenesis of SAPHO syndrome." (PMID 39286247, 2024). "Specifically, IL-8 has been shown to upregulate the production of TNF-α and IL-1β, creating a feedback loop that amplifies the inflammatory response, which is crucial for sustaining chronic inflammation characteristic of SAPHO syndrome." (PMID 39286247, 2024). "This article reviews the cytokines involved in the pathogenesis of SAPHO syndrome, such as tumor necrosis factor α (TNF-α), interleukin 1β (IL-1β), IL-6, IL-10, and transforming growth factor-β (TGF-β), and discusses their potential as intervention points for treatment." (PMID 39286247, 2024). "SAPHO syndrome is a chronic autoimmune disease that is manifested by raised levels of different inflammatory cytokines and neutrophil stimulation; among these changes, the upregulation of TNF-alpha, interleukin (IL)-8, IL-17, and IL-1b was recorded." (PMID 39233977, 2024). "In SAPHO syndrome, IL-10’s regulatory function potentially alleviates chronic inflammation and autoimmune responses by reducing the production of pro-inflammatory cytokines such as tumor necrosis factor α (TNF-α) and interleukin-1β (IL-1β)." (PMID 39286247, 2024).
sinusitis (4 papers, 2012 to 2024). An acute or chronic inflammatory process affecting the mucous membranes of any sinus cavity. "Furthermore, we investigated the nasal colonization of S. pyogenes, determined cytokine (TNF-α, IL-1β, and IL-6) levels, and conducted a splenocyte proliferative assay in a murine sinusitis model." (PMID 29853978, 2018).
spinal cord ischemia (4 papers, 2020 to 2025). Reduced blood flow to the spinal cord which is supplied by the anterior spinal artery and the paired posterior spinal arteries. "Additionally, some studies showed that IL-4 and IL-13 suppressed the expression and production of pro-inflammatory cytokines (TNF-α and IL-1β) in the spinal cord of animal models of spinal cord ischemia." (PMID 34679060, 2021). "For example, TLR4 mediates NF-κB/IL-1β activation which can aggravate the inflammatory injury of the blood spinal cord barrier (BSCB) and nerve cells after spinal cord ischemia reperfusion." (PMID 36714328, 2023).
ST Elevation Myocardial Infarction (4 papers, 2020 to 2025). A myocardial infarction that produces elevation in the ST segments of the ECG. "ST-elevation myocardial infarction (STEMI) patients with elevated inflammatory markers (e.g. hsCRP) have increased circulating IL-1β and NET-associated TF, while mouse models of thrombosis have reduced NET-associated TF and delayed thrombotic occlusion when IL-1β is blocked." (PMID 33391283, 2020). "IL-1β was associated with myocardial dysfunction and non-infarcted left ventricular mass 1-year after ST-elevation myocardial infarction (STEMI) and served as a potential predictor for maladaptive remodeling of the myocardium following AMI and reperfusion." (PMID 38256155, 2024).
Trichiasis (4 papers, 2012 to 2019). Inversion and rubbing of the eyelashes against the globe of the eye. "This identified a variety of pro-inflammatory (IL1B, TNFA, S100A7, CXCL5, NOS2A) and tissue remodelling factors (MMP7, MMP9 and MMP12), which were associated with conjunctival scarring and trichiasis before surgery." (PMID 23285311, 2012). "Previous studies have shown that a number of innate epithelial pro-inflammatory mediators (IL1B, S100A7, CXCL5), matrix factors (SPARCL1, CTGF, collagens) and matrix metalloproteinases (MMPs 7, 9, 12) are associated with progressive trachomatous scarring, trichiasis and post-operative trichiasis." (PMID 37426632, 2019). "By staining tissue sections with dyes and specific antibodies, pro-inflammatory signaling molecules IL-1β and S100A7 and pro-fibrotic growth factor CTGF were found to be more highly expressed in individuals with trichiasis." (PMID 27249027, 2016). "The upregulation of pro-inflammatory mediators and cell markers (CCL2, CCL3, CXCL5,IL1B, IL6, CHUK, FUT4 andPTPRC) is indicative of higher levels of inflammation and leukocyte infiltration in the conjunctival tissue of patients who developed ECA following trichiasis surgery." (PMID 37426632, 2019).
tuberous sclerosis (4 papers, 2016 to 2022). Hereditary disease characterized by seizures, intellectual disability, developmental delay, and skin and ocular lesions. "In GG, as in epileptogenic focal malformations (i.e., tuberous sclerosis complex, TSC), there is evidence of sustained neuroinflammation with involvement of the pro-inflammatory cytokine IL-1β." (PMID 36289354, 2022).
upper respiratory tract infections (4 papers, 2012 to 2025). "Long-term systemic neutralization of IL-1β by Canakinumab may increase the risk of serious upper respiratory tract infections, gastrointestinal disorders and vertigo, and decrease the quality of life of both patients and informal caregivers." (PMID 34290297, 2021). "However, long-term systemic neutralization of IL-1β by Canakinumab may cause severe adverse events such as serious upper respiratory tract infections and inflammation, thereby decreasing the quality of life of patients." (PMID 34290297, 2021). "Present study also showed that IL-1β mRNA expression in mandibular lymph node (one of regional lymph node of nasopharynx) was increased by influenza virus infection but downregulated by the administration of SHS from 2 hours p.i. to 4 days p.i. on upper respiratory tract infection." (PMID 23346216, 2012). "Nasopharyngitis (ROR 2.31, 95% CI: 2.1–2.54) and upper respiratory tract infections (ROR 2.6, 95% CI: 2.17–3.11) were notable, indicating compromised mucosal immunity, a key defense mechanism where IL-1β is essential for pathogen clearance." (PMID 41471316, 2025).
Vertigo (4 papers, 2021 to 2025). An abnormal sensation of spinning while the body is actually stationary. "After performing the Epley repositioning maneuver in the vertigo group, a statistically significant decrease in IL-1β levels was observed at the first and third months of follow-up." (PMID 38696405, 2024). "Of note, our finding that IL-1β levels are elevated in 75% patients with MD of active phase, but 25% patients with MD of quiescent phase, which suggests that vertigo episodes may lead to increased IL-1β levels." (PMID 36872329, 2023).
vivax malaria (4 papers, 2012 to 2021). "Asymptomatic vivax malaria patients presented a similar number of variables with significant concentrations increases (mainly IFN-γ, IL-10 and direct bilirubin) and decreases (such as CXCL10, IL-1β, IL-4 and indirect bilirubin)." (PMID 31233500, 2019).
AA amyloidosis (3 papers, 2013 to 2024). Secondary amyloidosis is a form of amyloidosis, that complicates chronic inflammatory disorders (mainly rheumatoid arthritis) and is characterized by the aggregation and deposition of amyloid fibrils composed of serum amyloid A protein, an acute phase reactant. "Among those, IL-1β is closely related to AA amyloidosis as SAA levels rapidly decline in patients undergoing IL-1β-inhibition (ClinicalTrials.gov, NCT00069329)." (PMID 39080494, 2024). "Indeed, proinflammatory cytokines (IL-1β, IL-6, and TNF-α) produced by antitumor lymphocytes or macrophages can induce SAA production and development of AA amyloidosis." (PMID 24558629, 2013).
Acidosis (3 papers, 2013 to 2020). Abnormal acid accumulation or depletion of base. "Acidosis and IL-1β increased nitrite/nitrate release, but increases were moderate at 2% O2 and significantly reduced at <1% O2." (PMID 23850530, 2013). "Acidosis and exposure to IL-1β resulted in significant reduction in GSH:GSSG ratio." (PMID 25998424, 2015).
acute GVHD (3 papers, 2014 to 2025). "To analyze an association between the genotypes IL-1α rs1800587, IL-1β rs16944, and IL-1β rs1143627 of recipients and donors and the occurrence of acute GVHD, we compared those who experienced clinically significant acute GVHD." (PMID 41291248, 2025). "These downstream effector molecules have been shown to modulate GVHD as antibody-mediated neutralization of IL-1β resulted in less severe acute GVHD in mice." (PMID 25101080, 2014). "Data on inflammasomes in allo-HSCT are not yet abundant, but NLRP3 and possibly other inflammasomes that sense endogenous danger signals such as ATP and uric acid and induce IL-1β release seems to have a role in the pathogenesis of acute GVHD." (PMID 25101080, 2014). "Notably, in humans, IL-1β blockade during the period of initial T-cell activation had no impact on the cumulative incidence of acute GVHD." (PMID 33643294, 2020).
aggressive periodontitis (3 papers, 2015 to 2024). "In studies of aggressive periodontitis (PDag) and chronic PD (CPD), 6 proinflammatory mediators (IL-1β, IL-6, IFN-γ, TNF-α, IL-17, and IL-12) and 2 common anti-inflammatory mediators (TGF-β and IL-4) were involved." (PMID 26339136, 2015).
allergic conjunctivitis (3 papers, 2011 to 2026). "A study reported increases in IL-1β, IL-2, IL-5, IL-6, IL-12, IL-13, in seasonal allergic conjunctivitis (SAC), vernal keratoconjunctivitis (VKC) and atopic keratoconjunctivitis (AKC), while IL-4, IFN-γ and IL-10 levels were increased in SAC and VKC compared to controls." (PMID 21298010, 2011).
alopecia (3 papers, 2024 to 2025). Hair loss usually from the scalp. "In an alopecia model, XFZYD can significantly inhibit the levels of IL-6, IL-1β, and TNF-α in serum and skin tissue." (PMID 40430532, 2025).
aphthous ulcer (3 papers, 2015 to 2025). "Additionally, a meta-analysis of 10 case-control studies (including 884 recurrent aphthous ulcer patients and 1,104 control participants) revealed that IL-1β gene mutations may increase susceptibility to recurrent aphthous ulcers." (PMID 41560733, 2025). "In this study, Corchorus olitorius seed extract displayed remarkable wound healing activity in the treatment of recurrent minor aphthous ulceration (RMAU) by accelerating wound closure rate, enhancing TGF-β, as well as TNF-α, expression, and suppressing inflammatory markers (TNF-α, and IL-1β)." (PMID 36296628, 2022).
appendicitis (3 papers, 2022 to 2025). Acute inflammation of the vermiform appendix. "The aim of the present study was to evaluate how the Th1 and Th17-associated cytokines IL-1α, IL-1β, IL-2, IL-6, IL-10, IL-17A and tumor necrosis factor beta (TNF-β) are associated with the risk of complicated appendicitis in children." (PMID 38409170, 2024). "This prospective cohort study aimed to evaluate the association between serum concentrations of the Th1-associated cytokines interleukin (IL)-1α, IL-1β, IL-2, IL-6, IL-10, IL-17A and tumor necrosis factor beta (TNF-β) and the risk of complicated appendicitis in children." (PMID 38409170, 2024). "High serum concentrations of IL-6 were associated with an increased risk of complicated appendicitis in children, whereas serum concentrations of IL-1α, IL-1β, IL-2, IL-10, IL-17A and TNF-β were not." (PMID 38409170, 2024). "A study investigating seventeen different cytokines in patients with appendicitis showed no statistically significant changes in preoperative levels of cytokines such as IFN-α and IL-1β." (PMID 40150581, 2025).
Arthralgia (3 papers, 2021 to 2023). "Elevated expression levels of interleukin-1β (IL-1β) are found in the synovial fluid of TMJOA patients, and the expression of IL-1β in cartilage and synovial tissue is closely associated with OA severity and arthralgia." (PMID 36145533, 2022).